BALR6 (B-cell acute lymphoblastic leukemia associated long RNA 6)
Synonyms: BALR-6
Gene: Long non-coding RNA gene on chromosome 3 (17,860,922 to 18,041,541, forward strand). Ensembl gene ENSG00000274840.
Diseases named in the same sentence as BALR6 in open-access papers:
BALR6 is named in the same sentence as 1 disease in open-access papers, as found by Europe PMC text mining. Sharing a sentence is not in itself a finding about the gene and the disease. The quoted sentences say what the papers report.
leukemia (1 paper, 2015). A malignant (clonal) hematologic disorder, involving hematopoietic stem cells and characterized by the presence of primitive or atypical myeloid or lymphoid cells in the bone marrow and the blood. "This suggests that the high expression of BALR-6 in B-ALL could represent a stage-specific expression pattern in leukemia derived from early stages of B-cell development." (PMID 26694754, 2015).